RUNX3 (RUNX family transcription factor 3)
Diseases named in the same sentence as RUNX3 in open-access papers (continued):
Sharing a sentence is not in itself a finding about the gene and the disease.
pancreatic cancer (continued). "It is thought that these are one of the tumour suppressor genes in pancreatic cancer, and we think that RUNX3 may also be a candidate." (PMID 18475302, 2008). "Furthermore, RUNX3 is located on the distal portion of the short arm of human chromosome 1 (1p36), which is commonly deleted in a variety of human cancers, including pancreatic cancer." (PMID 18475302, 2008). "Our study further supports a role for RUNX3 in pancreatic cancer." (PMID 18475302, 2008). "Interestingly, 1p36, where RUNX3 exists, is a region commonly deleted in a wide variety of human carcinomas, including pancreatic cancer." (PMID 18475302, 2008). "RUNX3 locus 1p36 is commonly deleted in a variety of human cancers, including pancreatic cancer." (PMID 18475302, 2008). "Interestingly, increased expression of Runx3 has also been observed in approximately one-third of pancreatic cancer cases." (PMID 17876328, 2007). "Therefore, we examined genetic and epigenetic alterations of RUNX3 in human pancreatic cancer." (PMID 18475302, 2008). "Our finding that the survival in methylated cases in RUNX3 gene was significantly worse than that in unmethylated patients is compatible with this hypothesis, although pointing to a tumour suppressor role for RUNX3 in pancreatic cancer." (PMID 18475302, 2008). "Therefore, the genetic and epigenetic alterations in RUNX3 may have an important role in pancreatic cancer." (PMID 18475302, 2008). "We propose that inactivation of RUNX3 plays an important role in alteration of the TGF-β signalling pathway and in the tumorigenesis of pancreatic cancer." (PMID 18475302, 2008). "Therefore, RUNX3 may be an important tumour suppressor gene related to pancreatic cancer." (PMID 18475302, 2008). "Additionally, miR-20-5p could target ribonucleotide reductase subunit M2 (RRM2) to regulate the gemcitabine chemosensitivity in pancreatic cancer cells and enhance the growth of triple-negative breast cancer (TNBC) cells by targeting Runx3, Bim, and p21." (PMID 34294156, 2021). "If the combination of RUNX3 and SMAD4 status could predict the behavior of PDAC, analyzing RUNX3 and SMAD4 protein expression status by immunohistochemistry in resected or biopsied PDAC tissues would greatly benefit pancreatic cancer patients by helping to guide treatment plans." (PMID 29100342, 2017). "Hence, the metastatic pancreatic cancer cells do not express RUNX3 gene." (PMID 18475302, 2008). "We first examined DNA samples obtained by microdissection from the 32 primary pancreatic cancer tissues and corresponding noncancerous tissues for LOH using two microsatellite markers, D1S234 and D1S247, which are close to the RUNX3 locus." (PMID 18475302, 2008). "Runx3, a member of the same family, is overexpressed in bulk PDAC tissues, but almost absent in a large group of cultured pancreatic cancer cell lines due to promoter hyper-methylation." (PMID 17876328, 2007).
lung adenocarcinoma (21 papers, 2014 to 2026). A carcinoma that arises from the lung and is characterized by the presence of malignant glandular epithelial cells. "Generally, RUNX3 inactivation is frequently associated with human lung adenocarcinoma in a K-Ras-mutated background." (PMID 30535344, 2019). "Runt-related transcription factor 3 (RUNX3) is one such tumor suppressor whose inactivation is considered to be an early pivotal event in lung adenocarcinoma pathogenesis." (PMID 38612589, 2024). "RUNX3 is a tumor suppressor that prevents lung adenocarcinoma, and its inactivation plays an important role in lung tumorigenesis." (PMID 37438719, 2023). "RUNX3 is ideally inactivated in lung adenocarcinoma induced by K-Ras, suggesting its potential role as a tumor suppressor in lung adenocarcinoma." (PMID 32765634, 2020). "Next, we investigated whether there is a clinical connection between CLDN1 and RUNX3 expression with respect to the survival of patients with lung adenocarcinoma." (PMID 32754286, 2020). "Although K-Ras-induced lung adenocarcinoma development can proceed via multiple pathways, the frequent inactivation of RUNX3 by epigenetic silencing in K-Ras-induced human lung adenocarcinoma suggests that RUNX3 inactivation prior to K-Ras activation is a major contributing pathway." (PMID 30535344, 2019). "Undoubtedly, K-Ras-induced lung adenocarcinoma development can proceed via multiple pathways; nonetheless, the high frequency of Runx3 inactivation in K-Ras-induced mouse and human lung adenocarcinoma suggests that a major pathway involves Runx3 inactivation before K-Ras activation." (PMID 25961920, 2016). "Therefore, CLDN1 and RUNX3 are good prognostic markers for lung adenocarcinoma." (PMID 32754286, 2020). "Interestingly, RUNX3 inactivation in KRAS driven lung adenocarcinoma has been shown to accelerate malignant progression and it will be of interest to test, whether RUNX interferes with YAP-FOS/AP1 co-operation in mediating EMT and malignant tumor progression." (PMID 29581836, 2018). "Study implicated a central role of RUNX3 downregulation in lung adenocarcinoma occurrence that may be independent of other well-known cancer-related pathways and suggested potential diagnostic implications." (PMID 25948105, 2015). "We used multiplex immunohistochemistry to assess and quantify cells co-expressing CD3 and RUNX3 in three cohorts consisting of 452 colon adenocarcinoma (COAD), 239 lung adenocarcinoma (LUAD) and 307 lung squamous cell carcinoma (LUSC) patients." (PMID 41644763, 2026). "In particular, RUNX3 is downregulated in most K-RAS-activated human and mouse lung adenocarcinomas (ADCs)." (PMID 36899846, 2023). "The regulation of RUNX3 expression and activity pathway detected in LUAD has been reported to accelerate malignant progression of lung adenocarcinoma." (PMID 36167504, 2022). "The A549 human lung adenocarcinoma cell line highly expresses TLR9 and also exhibits positive expression of the Runt-related transcription factor 3 (Runx3)." (PMID 24748977, 2014). "Furthermore, we analyzed the expression of RUNX3, IKZF1, and MEF2B in lung adenocarcinoma and normal lung tissues using TCGA data, and the analysis indicated that the three transcription factors were all downregulated in lung adenocarcinoma tissues." (PMID 40068093, 2025). "For example, Runx3 forms a complex with BRD2 in a KRas-dependent manner in the early stages of the cell cycle, resulting in the inactivation of Runx3 and promoting the development of lung adenocarcinoma." (PMID 36171897, 2022).
lung adenocarcinoma (continued). "Runx3 is expressed in nearly all lung epithelial cells, but silenced in most KrasG12D-induced lung adenocarcinomas, implying that KrasG12D can induce adenomas when it is expressed in cells that do not express Runx3 or some other critical gene." (PMID 25961920, 2016).
ovarian carcinoma (18 papers, 2013 to 2024). A malignant neoplasm originating from the surface ovarian epithelium. "Conversely, alternative investigations have suggested that the hypomethylation and expression of the RUNX3 gene in epithelial ovarian cancer tissue and cell lines are linked to an unfavorable prognosis." (PMID 38384812, 2024). "Transfecting RUNX3 transcript variant 1 and 2 into the two respective ovarian cancer cells lines resulted in variable changes of cisplatin sensitivity." (PMID 29342962, 2018). "In contrast to CaMKIINα, we see direct effects on the cisplatin sensitivity when overexpressing RUNX3 transcript variants in the analyzed ovarian cancer cell lines." (PMID 29342962, 2018). "have provided evidence of a significant association between the upregulation of RUNX3 and resistance to RBMO chemotherapy in ovarian cancer cases." (PMID 38384812, 2024). "Nevertheless, the current literature presents contradictory results regarding the specific function of RUNX3 in ovarian cancer." (PMID 38384812, 2024). "On the other hand, RUNX3 was shown to promote cell proliferation in ovarian cancer cells, indicating that RUNX3 can also play an oncogenic role in cancer cells." (PMID 37641472, 2023). "Conversely, RUNX3 is overexpressed and exhibits oncogenic activities in ovarian cancers, basal cell carcinomas, and head and neck cancers." (PMID 34722267, 2021). "In earlier studies, we showed that RUNX3 methylation in ovarian carcinoma patients has a prognostic value and that RUNX3 protein isoforms function differently in vitro." (PMID 33530588, 2021). "Aim of the present study was the functional characterization of CaMKIINα and RUNX3 in ovarian cancer cell lines—specifically in isogenic pairs of platinum-sensitive and -resistant A2780 and SKOV3." (PMID 29342962, 2018). "Then, in ovarian cancers and head and neck cancers, RUNX3 showed oncogenic activity." (PMID 34722267, 2021). "Paradoxically, RUNX3 has also been reported to play a carcinogenic role in basal cell carcinoma, head and neck squamous cell carcinoma, and ovarian cancer, which could promote tumor frequency and probability." (PMID 33401247, 2020). "Some of the reported hypermethylated genes in ovarian cancer are BRCA1, RASSF1A, TGFBI, DOK1, RUNX3, and CAMK2N1." (PMID 38627856, 2024). "The methylation of opioid-binding protein/cell adhesion molecules like OPCML, Runt-related transcription factor 3 (RUNX3), and tissue factor pathway inhibitor 2 (TFPI2) genes was studied in ovarian cancer patients using methylation-specific NGS." (PMID 38275400, 2024). "RUNX3 is generally considered as a TSG in human neoplasia as a multitude of epithelial cancers exhibit inactivation of RUNX3, including ovarian carcinoma, although oncogenic function of RUNX3 in EOC was also suggested." (PMID 24124450, 2013). "RUNX3 has been shown to be a prognostic biomarker for a variety of cancers, including breast, gastric, colorectal, and ovarian cancer, and there is a negative correlation of RUNX3 inactivation and patient survival." (PMID 36899853, 2023).
acute myeloid leukemia (15 papers, 2016 to 2024). Acute myeloid leukemia (AML) is a group of neoplasms arising from precursor cells committed to the myeloid cell-line differentiation. "There are three RUNX genes (RUNX1, RUNX2, and RUNX3) in humans that encode acute myeloid leukemia (AML), the alpha subunit of polyomavirus enhancer-binding protein 2 (PEBP2α), or core-binding factor subunit α (CBFα)." (PMID 36231060, 2022). "Inhibitors of the WNT pathway, including RUNX3, are frequently methylated and therefore inactivated in pathologies such as acute myeloid leukemias, or gastrointestinal cancers." (PMID 37371794, 2023). "For example, inactivating RUNX1 mutations frequently occur in acute myeloid leukemia, where upregulation of RUNX2 or RUNX3 exhibits anti-leukemic effects." (PMID 30216339, 2018). "Moreover, in one of our earlier studies the RUNX1 and RUNX3 expression level assessment was performed on a group of patients diagnosed with acute myeloid leukemia (AML)." (PMID 36005134, 2022). "RUNX3 is a transcription factor dysregulated in acute myeloid leukemia (AML)." (PMID 35490198, 2022). "The Runt-related transcription factor (RUNX) family, historically known as the polyoma enhancer-binding protein 2 α (PEBP2α), acute myeloid leukemia (AML) and core binding factor α (CBFα) family of proteins, comprises three members: RUNX1, RUNX2 and RUNX3." (PMID 36831308, 2023). "Genetic alterations of these genes (CBFB, RUNX1, RUNX2, and RUNX3) can alter normal binding to DNA by CBF, thus resulting in a failure of hematopoiesis or hematologic malignancies, particularly acute myeloid leukemia (AML)." (PMID 36011278, 2022).
non-small cell lung carcinoma (13 papers, 2007 to 2025). A group of at least three distinct histological types of lung cancer, including non-small cell squamous cell carcinoma, adenocarcinoma, and large cell carcinoma. "Other studies have shown that miR-17-5p participates in regulatory T-cell-mediated immune escape of non-small cell lung cancer cells by targeting RUNX family transcription factor 3 (RUNX3)." (PMID 41453319, 2025). "Another study found that RUNX3 expression is lost in non-small cell lung cancer (NSCLC), leading to the upregulation of CCL5 and CCL19 in NSCLC cells, which was associated with tumor-associated bone destruction." (PMID 38430423, 2024). "RUNX3 mislocalization from the nucleus to the cytoplasm occurs in various advanced carcinomas, including non-small cell lung cancer, and inactivates tumor suppression, suggesting that nuclear RUNX3 plays a key role in cancer suppression." (PMID 38683453, 2024). "The purpose of this study is to investigate the significance of RUNX3/H3K27me3 co-expression in surgically resected non-small-cell lung cancer (NSCLC) patients." (PMID 35368900, 2022). "Previous studies demonstrated that RUNX3 overexpression inhibited the proliferation of non-small-cell lung cancer cells, consistent with our results." (PMID 36518886, 2022).
lymphoma (12 papers, 2008 to 2025). A malignant (clonal) proliferation of B- lymphocytes or T- lymphocytes which involves the lymph nodes, bone marrow and/or extranodal sites. "RUNX3 expression was shown to be greater in esophageal cancer, head and neck cancers, kidney cancer, lymphoma, and sarcoma than in other malignancies." (PMID 35522574, 2022). "Then, we overexpressed RUNX3 in lymphoma cells with ARID1A loss (het), which, unlike HEK 293 T cells, endogenously express ETS1." (PMID 39843653, 2025). "Finally, we aimed to directly demonstrate that ETS1 and RUNX3 cooperate in regulating FAS expression in lymphoma cells." (PMID 39843653, 2025). "C-MYC is a well-known oncogene in lymphomas and is overexpressed in ENKTL, likely driven by LMP1 and EBV infection and causing upregulation of downstream targets EZH2 and RUNX3, the latter of which is a master transcriptional regulator and a putative oncogene in ENKTL." (PMID 36900160, 2023). "Additionally, murine leukemia virus integration in the RUNX3 loci, resulting in overexpression of P1 derived RUNX3 TV1, caused lymphomas, and revealed a potential oncogenic function." (PMID 29342962, 2018). "MYC and RUNX3, which are regulators of cellular processes such as proliferation and differentiation, were among the transcription factors with indirect effects in lymphomas." (PMID 18358079, 2008). "RUNX3 is required for silencing of CD4, and our results suggest that this silencing plays a significant role in RUNX3-induced progression of lymphomas." (PMID 18358079, 2008). "C-MYC inhibitors are of particular interest in multiple aggressive lymphomas, and treatment of ENKTL cell lines with a small-molecule novel MYC inhibitor caused downregulation of both MYC and RUNX3 and, subsequently, apoptosis." (PMID 36900160, 2023). "While conjugate formation of lymphoma cells and T cells were not affected by ARID1A genotype, cells with ARID1A loss were less sensitive to T cell-mediated apoptosis, and overexpression of RUNX3 restored sensitivity towards T cell-mediated killing." (PMID 39843653, 2025).
psoriasis (12 papers, 2014 to 2024). An autoimmune condition characterized by red, well-delineated plaques with silvery scales that are usually on the extensor surfaces and scalp. "Several studies have implicated RUNX3 in the development of immune-related diseases including Crohn’s disease, ankylosing spondylitis, psoriasis and ulcerative colitis, and SNPs which disrupt RUNX binding sites have also been associated with RA." (PMID 30176915, 2018). "For example, runt-related transcription factor 3 (RUNX3) has been reported to be a susceptibility gene for psoriasis and promotes Th1 cells differentiation through binding with T-bet." (PMID 29715312, 2018). "Furthermore, runt-related transcription factor 3 (RUNX3) is a susceptible gene for psoriasis, and its overexpression promotes Th22 cell secretion of IL-22." (PMID 36839448, 2023). "Notably, loss of RUNX3 impairs Th17 and Th22 differentiation, both of which are required for the pathogenesis of psoriasis." (PMID 35511484, 2022). "Notably, RUNX3, as a psoriasis susceptibility gene, plays an important role in the differentiation of T cells in psoriasis, through both modulating the balance of Th1/Th2 and regulating the differentiation of Th17 and Th22 cells." (PMID 33718413, 2021). "Many studies have confirmed the role of the RUNX3 gene in the pathogenesis of rheumatoid arthritis, lupus, and psoriasis." (PMID 38956704, 2024). "From a pathological aspect, a genome-wide association study (GWAS) suggested the possible involvement of Runx1 and Runx3 in psoriasis, an abnormal manifestation of keratinocyte proliferation and differentiation." (PMID 36077435, 2022). "Studies have shown that RUNX3 is involved in the differentiation of Th22 cells in patients with psoriasis." (PMID 34434945, 2021). "The number of Th22 cells decreased significantly after RUNX3 levels of CD4+ T cells from psoriasis patients were restricted by RNA interference." (PMID 34434945, 2021). "A recent study found that increased miR-138 regulates the balance of Th1/Th2 through inhibiting RUNX3 expression in CD4+ T cells in psoriasis." (PMID 29715312, 2018). "In a study conducted by Fu and coworkers it is observed that decreased expression of miRNA-138 in CD4+ T-cells increases the expression of runt-related transcription factor 3 (RUNX3) and the ratio of Th1/Th2 in the cells obtained from patients suffering from psoriasis." (PMID 32038627, 2019). "Taken together, these results suggest that RUNX3 may act a promising therapeutic target for psoriasis." (PMID 29715312, 2018). "The inhibition of RUNX3 reduced the relevant cytokines levels, and decreased the frequency of Th17 and Th22 cells in CD4+ T cells from psoriasis patients." (PMID 29715312, 2018).
ankylosing spondylitis (11 papers, 2013 to 2022). An autoimmune chronic inflammatory disorder characterized by inflammation in the vertebral joints of the spine and sacroiliac joints. "RUNX3, a transcription factor influencing T lymphocyte development, has been associated with celiac disease and ankylosing spondylitis and was hypermethylated in systemic lupus erythematosus patients." (PMID 26158728, 2015). "Our purpose is to examine the influence of PPARGC1B, RUNX3 and TBKBP1 polymorphisms on the susceptibility to and the severity of ankylosing spondylitis in Chinese ethnic majority Han population." (PMID 23637848, 2013).